MUC1 (mucin 1, cell surface associated)
Diseases named in the same sentence as MUC1 in open-access papers (continued):
Sharing a sentence is not in itself a finding about the gene and the disease.
pancreatic cancer (continued). "It has also been shown that EGFR and MUC1 will accumulate in the perinuclear space in pancreatic cancer cells after exposure to EGF stimuli, similar to our current findings." (PMID 29464085, 2018). "Yet, an exponential increase in MUC1 expression occurs during early stages of pancreatic cancer development." (PMID 29467938, 2018). "The anti-hMUC1 monoclonal antibody immunoprecipitated MUC1 in the pancreatic cancer cell lines Capan-1, Capan-2 and CFPAC-1; however, it was unable to detect MUC1-C by western blot analysis." (PMID 29987260, 2018). "Combination therapy using MUC1-mRNA-transfected DCs, MUC1-CTLs and gemcitabine was evaluated in 42 patients with unresectable or recurrent pancreatic cancer." (PMID 29946224, 2018). "Studies have shown increased expression of MUC1 in pancreatic cancer in contrast to the low expression levels observed of MUC1 in the luminal surfaces of a normal control pancreases." (PMID 29987260, 2018). "To examine if the anti-hMUC1 monoclonal antibody recognizes MUC1 protein in pancreatic cancer cells, we performed western blot analysis with lysates from Capan-1, Capan-2, CFPAC-1 and PANC-1 pancreatic cancer cell lines." (PMID 29987260, 2018). "MUC1, which participates in immunosuppression and the progression of pancreatic cancer, can be regulated by DNA methylation and histone H3 lysine 9 modification." (PMID 30060755, 2018). "When the anti-hMUC1 antibody was injected into a xenograft mouse model and traced using an in vivo imaging system, we observed that the anti-hMUC1 antibody was localized to MUC1-expressing pancreatic tumors." (PMID 29987260, 2018). "According to immunohistochemistry analysis using a pancreatic cancer tissue array and the anti-hMUC1 antibody, MUC1 was highly expressed in human pancreatic cancer tissues compared to normal tissues." (PMID 29987260, 2018). "Recently, we produced a monoclonal antibody (the anti-hMUC1 antibody) specific to the extracellular region of the MUC1 subunit MUC1-C to evaluate the utility of using anti-MUC1 antibodies in pancreatic cancer models." (PMID 29987260, 2018). "miR-29a is downregulated in pancreatic cancer cell-lines, a change which elevates invasiveness and proliferation, in part by increasing MUC1 expression." (PMID 28460473, 2017). "Nevertheless, genetic knockdown or pharmacological inhibition of ILK caused depleted MUC1-C expression in IL-6-treated pancreatic cancer cells, indicating that ILK is required to sustain STAT3-induced MUC1 upregulation by maintaining its stability." (PMID 28692035, 2017). "CA19-9 and DU-PAN2 are clinically used markers for MUC1 in pancreatic cancers with the former being FDA approved." (PMID 28978023, 2017). "N-terminal fragments of MUC1 can be detected in the serum of pancreatic cancer patients by the CA15-3 serum assay, and MUC1 expression together with serum levels are associated with a poor prognosis and recurrence in resected patients." (PMID 28978023, 2017). "High MUC1-TM expression was observed in pancreatic cancer tissues, accompanied by a loss of MUC1-ARF expression [compare expression of MUC1-TM and MUC1-ARF in normal pancreatic tissue, to that seen in pancreatic cancer tissue]." (PMID 27768738, 2016). "Disease stabilization was also seen in multiple myeloma patients treated with the MUC1 signal peptide and in pancreatic cancer patients treated with dendritic cells pulsed with a 100-mer peptide." (PMID 27367740, 2016). "The pulsed DCs were administered in combination with MUC-1-specific T cells to patients with unresectable or recurrent pancreatic cancer." (PMID 27141395, 2016).
pancreatic cancer (continued). "Despite extensive study of MUC1 in the context of breast and pancreatic cancers, there is limited understanding of MUC1 in endometrial cancer beyond expression studies." (PMID 27092881, 2016). "Pancreatic cancers, known for their aggressive malignant phenotype, showed a loss of MUC1-ARF expression, as compared to high MUC1-ARF expression in epithelial cells from normal pancreatic tissue." (PMID 27768738, 2016). "There is increasing evidence between aberrant glycosylations or expression of mucin peptides and neoplasms, such as MUC1, MUC2, MUC5AC in pancreatic neoplasm; MUC1, MUC4 in Gastrointestinal neoplasms." (PMID 27374181, 2016). "In a similar study, PBMC-derived mature DCs from a pancreatic cancer patient were pulsed with MUC-1 peptide." (PMID 27141395, 2016). "These pancreatic cancer cells expressing high levels of MUC1 exhibited increased resistance to chemotherapeutic drugs such as gemcitabine and etoposide in comparison with cells that express low levels of MUC1." (PMID 27029067, 2016). "MUC1, a member of the mucin family of glycoproteins that is commonly overexpressed and aberrantly glycosylated in pancreatic cancer, is known to modulate the invasive and metastatic potential of cancer cells." (PMID 27220889, 2016). "This latter report provided evidence for a critical role of MUC1 directly regulating the expression of MDR genes in pancreatic cancer cells, and thus conferring drug resistance." (PMID 27029067, 2016). "Considering example of mucin glycoproteins (MUC1), it has been reported that each pancreatic cancer cell line expresses a unique pattern of MUC1 glycoforms." (PMID 26795117, 2016). "Previous studies demonstrated that MUC1 affects AP-1 regulation of target genes in pancreatic cancer cell lines." (PMID 27220889, 2016). "In the present study, we wished to study MUC1 targeting of human pancreatic cancer with the next goal of studying MUC1 targeting in our pancreatic cancer orthotopic xenograft (PDOX) models." (PMID 25815753, 2015). "The results of the present study demonstrate that MUC1 is an additional target for pancreatic cancer labeling and therapeutics delivery." (PMID 25815753, 2015). "Mice with pancreatic cancer cells growing in skin flaps were injected with anti-MUC1 (CT2) conjugated with DyLight 550 dyes into the tail vein." (PMID 25815753, 2015). "Recently, our lab has established that another important mucin family member, MUC1, regulates glucose metabolism in pancreatic cancer." (PMID 26046375, 2015). "Recently, we have demonstrated that another mucin family member MUC1 reprograms glycolytic metabolism in pancreatic cancer." (PMID 26046375, 2015). "The PAM4 antibody against Muc-1 is more specific for pancreatic cancer than antibodies to the other Muc-1 antigens that are observed in other tumors." (PMID 26579537, 2015). "The present results from subcutaneous and orthotopic tumor models demonstrate that MUC1 can target and visualize pancreatic cancer by making it fluorescent." (PMID 25815753, 2015). "Several authors have reported that the serum KL-6 concentration was measured in 44% of pancreatic cancer patients and that the KL-6 (MUC1) concentration of PJC specimens can be measured." (PMID 26451373, 2015). "Attempts have been made to detect MUC1 in the serum of patients and pancreatic cancer tissue with various methods." (PMID 25815753, 2015). "The proportion of MUC1 positive cells were 36.9% in BxPC3 and 24.4% in Panc1 pancreatic cancer cell lines, as observed with flow cytometry." (PMID 25815753, 2015). "Many studies have demonstrated that Muc-1 can be used as an ideal target in the diagnosis and treatment of pancreatic cancer." (PMID 26579537, 2015). "Mucin-1 (MUC1) is a membrane-bound hypoglycosylated phosphoprotein that is overexpressed in pancreatic tumors." (PMID 26266422, 2015). "Western blot and flow cytometric analysis confirmed the expression of MUC1 in human pancreatic cancer cell lines including BxPC-3 and Panc-1." (PMID 25815753, 2015).
pancreatic cancer (continued). "Both pancreatic cancer cell lines tested (BxPC-3 and Panc-1) had MUC1 expression observed with Western blotting." (PMID 25815753, 2015). "Merging with corresponding differential interference contrast microscopy confirmed that the fluophore-conjugated antibody reacted with MUC1 on the surface of the pancreatic cancer cells and produced fluorescence." (PMID 25815753, 2015). "MUC1 is a very attractive imaging biomarker for pancreatic cancer since it is overexpressed in approximately 90% of pancreatic cancer patients." (PMID 25815753, 2015). "We have previously reported adoptive immunotherapy (AIT) with CTLs stimulated by a MUC1-expressing human pancreatic cancer cell line, YPK-1, (MUC1-CTLs) for unresectable pancreatic cancer." (PMID 24947606, 2014). "We have recently published that MUC1 was detected in the circulation of pancreatic cancer patients in a stage-dependent manner." (PMID 24605110, 2014). "Induced MUC1-CTLs (HLA-A24/26) showed strong cytotoxicity against pancreatic cancer cell lines (YPK-1; HLA-A24, and YPK-3; HLA-A02) which expressed MUC1 antigen on the cell surface in an HLA- unrestricted manner." (PMID 24947606, 2014). "MUC4 stabilizes HER2 on the plasma membrane by inhibiting its internalization in pancreatic cancer, whereas MUC1 induces the internalization of EGFR and directs it to the nucleus for transcriptional upregulation of oncogenic factors." (PMID 25261375, 2014). "The Mucin aptamers are binding to short O-glycan-peptides (MUC1) on the surface of breast, colon, lung, ovarian, and pancreatic cancer cells." (PMID 24481022, 2014). "Patients with pancreatic cancer display high levels of circulating tumor MUC1 (CA19-9) that correlate with poor prognosis and disease recurrence." (PMID 24605110, 2014). "CA 19–9, a sialylated Lewis (Lea) antigen of the MUC1 protein, is another prognostic marker in pancreatic cancer, and serial measurements of CA 19–9 have been shown to be useful to monitor treatment response." (PMID 23530749, 2013). "The pulsed DCs were administered, along with autologous expanded MUC-1-specific T cells, to patients with unresectable or recurrent pancreatic cancer." (PMID 23509731, 2013). "Evidences suggest that circulating anti-MUC1-IgG is a favorable prognostic factor for pancreatic cancer." (PMID 23509731, 2013). "We evaluated the capacity of MUC1 to regulate the global transcription of microRNAs in pancreatic cancer cells expressing MUC1." (PMID 24143167, 2013). "MUC1 has been reported to enhance liver and lung metastasis in a mouse model of pancreatic cancer and high MUC1 expression has been correlated with metastatic tumor phenotype in human cancer." (PMID 24072600, 2013). "We examined the effects of MUC1 overexpression on global patterns of microRNA (miR) expression in pancreatic tumors, and report here alterations in expression of numerous microRNAs that are associated with cellular processes of tumor progression." (PMID 24143167, 2013). "We demonstrate here that overexpression of MUC1 and concomitant signaling through phosphorylation of the MUC1.CT alters the microRNA profile in pancreatic cancer cells." (PMID 24143167, 2013). "We evaluated expression of these microRNAs in a second pancreatic cancer cell line model system of MUC1 overexpression (Panc1) by quantitative RT-PCR." (PMID 24143167, 2013). "These MUC1-mRNA-transfected DC were able to induce MUC1-specific CD8+ T lymphocytes that can kill pancreatic cancer cells." (PMID 23509794, 2013). "We utilized miRCURY LNA microarrays (Exiqon) to evaluate expression of microRNAs in the context of MUC1 overexpression in pancreatic cancer cells." (PMID 24143167, 2013). "We sought to determine if there were correlations between miR-200c and relative levels of MUC1 expressed by pancreatic cancer cell lines, primary tumors and matched metastatic lesions." (PMID 24143167, 2013).
pancreatic cancer (continued). "A second pancreatic cancer cell line overexpressing MUC1, Panc1.MUC1, was investigated for phospho-MUC1.CT occupancy at the miR-200c/141 promoter." (PMID 24143167, 2013). "MUC1 is a type I transmembrane glycoprotein aberrantly overexpressed in various cancer cells including pancreatic cancer." (PMID 22912777, 2012). "It has been reported that MUC1 over-expressing pancreatic tumor cells have higher c-Met signaling activity and a greater tendency to metastasize when low levels of HGF are present in the tumor microenvironment." (PMID 22962849, 2012). "MUC1-c and HSP70 were found to co-immunoprecipitate, onfirming that HSP70 and MUC1 indeed interact in pancreatic cancer cells." (PMID 22912777, 2012). "The role of c-Met in the phosphorylation of MUC1 in pancreatic cancer progression has been recently reported." (PMID 22962849, 2012). "Recently, it has been reported that c-Met interacts with Mucin 1 (MUC1) and catalyzes the phosphorylation of the MUC1 cytoplasmic C-terminus in pancreatic cancer cells." (PMID 22962849, 2012). "A correlation was found to exist between aggressiveness of the cell line and expression of MUC1 in pancreatic cancer." (PMID 22912777, 2012). "Both inhibition of MUC1 expression by siRNA as well as inhibition of MUC1-c activity by GO-201 led to reduced proliferation and increased cell death in pancreatic cancer cells." (PMID 22912777, 2012). "Expression of MUC1 was studied in several pancreatic cancer cell lines at both the RNA and protein level." (PMID 22912777, 2012). "At the same time, MUC1 is known to be overexpressed in pancreatic cancer and play a role in cell survival in a number of cancer cell lines, but the exact mechanism has been elusive." (PMID 22912777, 2012). "Most pancreatic cancers also express a number of mucins (including MUC1, MUC3, MUC4, MUC5AC), and more recently described markers such as claudin 4 and claudin 18, several S-100 proteins, mesothelin and prostate stem cell antigen." (PMID 22458520, 2012). "Localization of MUC1 in lysosomes was further confirmed by co-staining pancreatic cancer cells with the lysosomal marker Lamp2." (PMID 22912777, 2012). "The C595 and PAI2-alpha conjugates are indicated for the treatment of micro-metastatic pancreatic cancer with over-expression of MUC1 and uPA receptors in post-surgical patients with minimal residual disease." (PMID 24212784, 2011). "For the treatment of pancreatic cancer, DCs have been engineered to produce interleukins (IL-18, IL-12) or the human tumor antigen mucin (MUC1)." (PMID 24212620, 2011). "In pancreatic cancer, DNA vaccination targeting MUC1 or survivin has been studied in murine models and resulted in antitumor immune responses." (PMID 21922022, 2011). "Both uPA and MUC1 have similar expression in pancreatic cancer tumors and the alpha conjugates of c595 and PAI2 have similar in vivo efficacy." (PMID 24212784, 2011). "The paper reviews the expression of the generic receptors MUC1 and uPAR by selected pancreatic cancer cell lines, human tumor xenografts and pancreatic cancer tumors in patients." (PMID 24212784, 2011). "In an MUC1 peptide vaccine, vaccination of 16 patients with resected or locally advanced pancreatic cancer with 100 mer MUC1 peptide and SB-AS2 adjuvant resulted in low but detectable MUC1-specific immune responses in some patients." (PMID 21922022, 2011). "In a phase I/II trials, vaccination for the patients with advanced pancreatic cancer using mutant K-ras, MUC1, or telomerase peptides was significantly associated with immune responses." (PMID 21922022, 2011). "Our results indicate that 213Bi-C595 is effective for pancreatic cancer spheroids up to 100 μm in diameter, and that targeting efficacy is in accordance with the expression of MUC1 in three cancer cell lines." (PMID 24212784, 2011). "Previous studies on MUC1 suppression in lung, breast and pancreatic cancer cells reported increased sensitivity to genotoxic drugs both in vitro and in vivo." (PMID 20492722, 2010).
pancreatic cancer (continued). "MUC1 transgenic mice (MUC1.Tg), which express MUC1 in a similar pattern and level as observed in humans, have been crossed with LStopL-KrasG12D pancreatic cancer developing mice." (PMID 24281201, 2010). "Adenovirus with MUC1 promoter driving human somatostatin receptor subtype 2 (hSSTR2) in PANC-1 pancreatic cancer cells demonstrates a significant inhibition of cell proliferation in MUC1+ pancreatic carcinoma." (PMID 24281201, 2010). "Our observations indicated that three intramuscular injections of pcDNA3.1-VNTR suppressed, in a MUC1-specific manner, the development of pancreatic cancer expressing MUC1 in C57BL/6 mice." (PMID 19534821, 2009). "Few studies, however, demonstrated the effect of the MUC1 DNA vaccine on the therapy of pancreatic cancer, and most studies have focused on the preventive effect of the DNA vaccine." (PMID 19534821, 2009). "Here we investigated the preventive and therapeutic effect of a MUC1 DNA vaccine on the pancreatic cancer." (PMID 19534821, 2009). "Recently, it was demonstrated that MUC1 is upregulated in blood of more than 90% of patients with pancreatic carcinoma." (PMID 19956730, 2009). "The same group has recently developed a bivalent 111In-DOTA-labeled antibody to MUC-1 and reported on successful gamma scintigraphy results in mice bearing s.c. xenografts of pancreatic carcinoma." (PMID 19956730, 2009). "On the basis of our findings, we report that the overexpression of MUC1 mucin on the surface of human pancreatic cancer cells impede the cytotoxic activity of 5-FU." (PMID 17912239, 2007). "The inhibition of MUC1 O-glycosylation in pancreatic cancer cells was confirmed by alterations in CD227 antibody association following exposure to benzyl-α-GalNAc." (PMID 17912239, 2007). "An open-label Phase 1 study of recombinant prime-boost poxviruses targeting CEA and MUC-1 in patients with advanced pancreatic cancer was conducted to determine safety, tolerability and obtain preliminary data on immune response and survival." (PMID 18039393, 2007). "In this study we tested the safety and feasibility of using poxviruses expressing CEA and MUC-1 with TRICOM as a vaccine treatment for patients with advanced pancreatic carcinoma." (PMID 18039393, 2007). "A short-term presumably HLA-unrestricted CTL line established by repeated stimulation of lymph node T cells obtained from a pancreatic carcinoma patient recognized and lysed MUC-1 positive pancreatic, breast, and ovarian carcinoma cells." (PMID 16281981, 2005). "In the present study, we first demonstrated the expression of the MUC1 antigen on human pancreatic cancer specimens and human pancreatic cancer cell lines using MAb C595." (PMID 15599383, 2004). "In the present study, we have demonstrated moderate to strong MUC1 expression on the majority of human primary pancreatic tumours and pancreatic cancer cell lines using MAb C595." (PMID 15599383, 2004). "Herein, we discuss the factors that contribute to the lethality of pancreatic cancer as well as the key role played by mucins, particularly MUC1 and MUC4, in the development and progression of the disease." (PMID 15494719, 2004). "Overexpression of MUC1 was found in ∼90% of tested tumour samples and the three pancreatic cancer cell lines." (PMID 15599383, 2004). "The aim of this study was to detect the expression of MUC1 in human primary tumour tissues and three pancreatic cancer cell lines (CAPAN-1, CFPAC-1 and PANC-1), and target MUC1-positive cancer cells in vitro using 213Bi-C595 alpha-immunoconjugate (AIC)." (PMID 15599383, 2004). "We have demonstrated moderate to strong MUC1 expression on the majority of human primary tumours and pancreatic cancer cell lines using MAb C595." (PMID 15599383, 2004). "It was also reported that increased MUC-1 expression correlates with the stage and grade of pancreatic cancer." (PMID 15599383, 2004).